MCL1 (MCL1 apoptosis regulator, BCL2 family member)
Description:
Involved in the regulation of apoptosis versus cell survival, and in the maintenance of viability but not of proliferation. Mediates its effects by interactions with a number of other regulators of apoptosis. Isoform 1 inhibits apoptosis. Isoform 2 promotes apoptosis.
Synonyms: Bcl2-L-3; BCL2L3; Mcl-1; C1orf138; ADAMTSL4-AS1; EAT; MCL1-ES; MCL1L; MCL1S; TM; mcl1/EAT
Tractability: Small molecule: a drug acting on it is in phase 2 or 3 trials; a structure with a bound ligand is known; a high-quality ligand is known; it has a binding pocket of medium quality; it belongs to a druggable protein family. Antibody: UniProt predicts a signal peptide or a membrane-spanning region. PROTAC: it is named in the literature on targeted protein degradation; UniProt records ubiquitination sites on it; ubiquitination databases record sites on it; its protein half-life has been measured; a small molecule that binds it is known.
Target class: Other cytosolic protein
Chemical probes: A-1210477 (high quality), JNJ-78394355 (high quality), ML311, PD134246, PD134247, PD134248, PD134249, PD134250, PD134251, PD134252, PD134253, PD134254, PD134255, PD134256, S63845 (high quality), TAPOTOCLAX (high quality)
Gene: Protein-coding gene on chromosome 1 (150,560,895 to 150,579,738, reverse strand). Ensembl gene ENSG00000143384.
Subcellular location: Membrane; Cytoplasm; Mitochondrion; Nucleus, nucleoplasm
Subcellular location (Human Protein Atlas): Mitochondria
Pathways (Reactome):
Disease: Signaling by ALK fusions and activated point mutants
Immune System: Interleukin-4 and Interleukin-13 signaling
Gene Ontology:
Molecular function: BH3 domain binding; protein binding; protein heterodimerization activity; channel activity; protein transmembrane transporter activity; BH domain binding
Biological process: DNA damage response; extrinsic apoptotic signaling pathway in absence of ligand; negative regulation of anoikis; negative regulation of apoptotic process; negative regulation of autophagy; negative regulation of extrinsic apoptotic signaling pathway in absence of ligand; positive regulation of apoptotic process; positive regulation of oxidative stress-induced neuron intrinsic apoptotic signaling pathway; response to cytokine; cell fate determination; cellular homeostasis; intrinsic apoptotic signaling pathway in response to DNA damage; mitochondrial fusion; positive regulation of neuron apoptotic process; release of cytochrome c from mitochondria; programmed cell death; protein transmembrane transport; regulation of apoptotic process; regulation of apoptotic signaling pathway; regulation of intracellular signal transduction; transmembrane transport
Cellular component: Bcl-2 family protein complex; membrane; mitochondrion; nucleus; cytoplasm; cytosol; mitochondrial outer membrane; nucleoplasm
Genetic constraint (gnomAD): Loss-of-function variants: 4 observed, 23.16 expected, observed/expected ratio (o/e) 0.17, 90% interval 0.084 to 0.4. The upper end of that interval is the gene's LOEUF score, 0.4, which puts it in group 1 of 6, group 1 being the genes least tolerant of losing a copy. Missense variants: 529 observed, 480.6 expected, observed/expected ratio (o/e) 1.1, 90% interval 1.02 to 1.18. Synonymous variants: 248 observed, 210.22 expected, observed/expected ratio (o/e) 1.18, 90% interval 1.06 to 1.31.
Homologues: Orthologues: chimpanzee MCL1 (99% identical), macaque MCL1 (97% identical), pig MCL1 (91% identical), dog MCL1 (89% identical), rabbit MCL1 (89% identical), rat Mcl1 (77% identical), mouse Mcl1 (76% identical), guinea pig MCL1 (60% identical), tropical clawed frog mcl1 (33% identical), zebrafish mcl1a (25% identical), zebrafish mcl1b (22% identical), Caenorhabditis elegans ced-9 (14% identical). Paralogues in human: BCL2 (14% identical), BAX (13% identical), BCL2L1 (13% identical), BOK (13% identical), BAK1 (13% identical), BCL2L2 (12% identical), BCL2A1 (11% identical), BCL2L10 (11% identical).
Diseases named in the same sentence as MCL1 in open-access papers:
MCL1 is named in the same sentence as 352 diseases in open-access papers, as found by Europe PMC text mining. Sharing a sentence is not in itself a finding about the gene and the disease. The quoted sentences say what the papers report.
breast carcinoma (261 papers, 2010 to 2026). "Increasing evidence indicates that overexpression of anti-apoptotic Bcl-2 family members, such as Bcl-2, Bcl-xL, and Mcl-1, is a major factor in breast cancer initiation, and is often associated with poor prognosis." (PMID 40949156, 2025). "Overexpression of anti-apoptotic members of the Bcl-2 family, such as Myeloid Cell Leukemia-1 (Mcl-1) and Bcl-2, has been linked to chemotherapy resistance in several cancers, including leukemia, lung cancer, and breast cancer." (PMID 39757310, 2025). "Copy number variations for the MCL1 gene, which has been implicated in apoptotic functions, have been reported in many hematologic as well as solid malignancies, including breast cancer." (PMID 38523186, 2024). "Targeting MCL1 inhibition in breast cancer-associated fibroblasts (bCAFs), which typically express MCL1, changes their phenotype and reverses their pro-invasive properties." (PMID 38256213, 2024). "By gaining a better understanding of the molecular mechanisms underlying TNBC's response to MCL1 inhibitors, these findings have the potential to enhance the efficacy of targeted therapy for this aggressive subtype of breast cancer." (PMID 38762181, 2024). "Previous human studies reported that high MCL-1 expression is associated with shorter survival times and poor outcomes in breast cancer, ovarian carcinoma, acute myeloid leukemia, and chronic lymphocytic leukemia." (PMID 39012900, 2024). "MCL-1 is overexpressed in breast cancer, lung cancer and other cancers, and is associated with resistance to chemotherapy drugs." (PMID 38609879, 2024). "More importantly, the main implication of the MCL1 gene in breast cancer is strongly associated with its anti-apoptotic role." (PMID 36902482, 2023). "High levels of Mcl-1 have been associated with high tumor grade and poor prognosis in breast cancer patients." (PMID 35053443, 2022). "The importance of targeting Mcl-1 was further demonstrated in studies showing its involvement in breast cancer-associated fibroblast-mediated resistance to the BH3 mimetics." (PMID 35053443, 2022). "Related to this, high MCL1 levels are associated with poor prognosis in certain subtypes of breast cancer, including TNBC, and MCL1 knockdown induces apoptosis in a subset of TNBC cell lines." (PMID 35008411, 2022). "MCL1 has been implicated in both the metastasis of clear cell renal carcinoma and recurrence of breast cancer." (PMID 34830758, 2021). "Amplification of MCL-1 is more frequent in clinical breast cancer datasets than BCL-2 and BCL-xL, and is associated with poor prognosis." (PMID 33883020, 2021). "In line with this, acute induction of whole body Mcl1 haploid loss restrained the growth of established mammary tumours and extended survival." (PMID 33785871, 2021). "The poor prognosis associated with MCL1 amplification or overexpression has been described in a spectrum of cancers, including non-small cell lung cancer, breast cancer, esophageal squamous cell carcinoma, and acute myeloid leukemia, but not in glioma." (PMID 33747896, 2020). "We show here that the BCL-2 dependency of luminal tumor cells is nevertheless mitigated by breast cancer-associated fibroblasts (bCAFs) in a manner that defines MCL-1 as another critical therapeutic target." (PMID 30631150, 2019). "Mcl-1 overexpression has been reported in breast cancer cells and has been linked with poor prognosis in breast cancer patients and resistance to drug-mediated apoptosis induction." (PMID 31404252, 2019). "Mcl-1 expression has been associated with chemoresistance and poor prognosis in breast cancer, and compounds that inhibit this protein can be a promising therapeutic strategy." (PMID 31614718, 2019). "Iterative mouse modeling and comparative oncogenomics analysis show that MYC-overexpression strongly reshapes the CNA landscape of BRCA1-deficient mammary tumors and identify MCL1 as a collaborating driver in these tumors." (PMID 30674894, 2019).
breast carcinoma (continued). "Here, we report an association between high MCL-1 protein expression in tumour epithelium and poor patient outcome in breast cancer." (PMID 29339815, 2018). "We, therefore, analysed MCL-1 protein expression by immunohistochemistry in a large tumour tissue microarray of 428 patients with primary operable breast cancer, and correlated MCL-1 expression with associated clinicopathological data." (PMID 29339815, 2018). "Myeloid cell leukemia 1 (MCL1) is an anti-apoptotic Bcl2 family member that is associated with poor prognosis of multiple myeloma and breast cancer." (PMID 29484127, 2018). "Our data demonstrate that high MCL-1 protein expression is associated with poor outcome in breast cancer and support the therapeutic targeting of MCL-1 in this disease." (PMID 29339815, 2018). "Here, we report associations between high MCL-1 and poor prognosis in specific subtypes of breast cancer including triple-negative breast cancer, an aggressive form that lacks targeted treatment options." (PMID 29339815, 2018). "The anti-apoptotic Bcl-2 family member, myeloid cell leukemia 1 (Mcl-1) has been implicated in promoting survival of many cancers, including breast cancer." (PMID 28301598, 2017). "A few studies have linked breast cancer progression and drug resistance to over-expression of pro-survival factors including Bcl-2, Mcl-1 and other BH3 family members." (PMID 29099748, 2017). "MCL-1 amplification occurs in approximately 30% of breast cancers and increased expression is associated with the acquisition of chemo-resistance and relapse, making MCL-1 an attractive therapeutic target." (PMID 27931239, 2016). "High cytoplasmic MCL-1 levels (Histoscore > 100) were modestly associated with improved breast cancer specific survival (log-rank Mantle Cox p = 0.04, hazard ratio = 0.54, 95% confidence interval 0.295–0.975)." (PMID 27931239, 2016). "Three independent MCL-1 mRNA probes corresponding to Variant 1 (200798_x_at) and full-length MCL-1 (214057_at and 214056_at) were investigated, and the breast cancer cohort was split into untreated and treated cases." (PMID 27931239, 2016). "Insulin-like growth factor-binding proteins (IGFBPs) derived from carcinoma-associated fibroblasts (CAFs) stabilized MCL-1 protein to protect breast cancer cells from cell detachment-induced death (anoikis)." (PMID 26035829, 2015). "The association of Syk with Mcl-1 expression was also tested in other breast cancer cells with different genetic backgrounds." (PMID 26720004, 2015). "Remarkably, MCL1 overexpression is associated with poor prognostic outcome in multiple myeloma, breast cancer, relapsing acute myeloid leukaemia and acute lymphocytic leukaemia, so the mechanisms that increase MCL1 levels are of paramount importance." (PMID 25386925, 2014). "Overexpression of Mcl-1 is associated with poor prognosis in many types of cancers including breast cancers." (PMID 23601074, 2013). "We found reduced ubiquitination of Mcl-1 and unstable association of Mcl-1 with its specific E3 ligase Mule in breast cancer cells treated with CHX." (PMID 21730980, 2011). "We also downregulated Mcl-1-associated HRF in breast cancer cell lines MDA-MB-231 with HRF siRNA and found a moderate increase in ubiquitination of Mcl-1 levels." (PMID 21730980, 2011). "In most of the CHX-treated breast cancer cell lines, we found increased stability of Mcl-1 associating proteins Puma and HRF." (PMID 21730980, 2011). "However, clinical and preclinical studies have revealed that pharmacological inhibition of Bcl-2 and Bcl-xL alone in breast cancer cells causes the induction of Mcl1, which then leads to drug resistance and failure to inhibit tumor growth." (PMID 36853387, 2023). "Thus the resistance of breast cancer cells to anti-apoptotic targeting of BH3 mimetics is associated with the influence of the stroma on the expression of Mcl-1." (PMID 35053443, 2022).
breast carcinoma (continued). "Furthermore, analysis of extensive breast cancer datasets reveals an association between MCL1 expression and markers of both stemness and an epithelial-to-mesenchymal transition (EMT)." (PMID 35349392, 2022). "The prevalence of MCL-1 upregulation in breast cancer suggests that it is required for tumor development, and associations between high MCL-1 and poor outcome may also indicate a role for MCL-1 in resistance to existing treatment regimen." (PMID 35349392, 2022). "This indicated a selective pressure against MCL1 loss in mammary tumors." (PMID 35053443, 2022). "In order to probe whether MCL-1 might be specifically associated with breast cancer stemness across human breast cancers we examined a number of tumour gene expression datasets." (PMID 33785871, 2021). "More importantly, Mcl-1 upregulation was associated with Dox resistance in breast cancer." (PMID 33919902, 2021). "MMTV-PyMT mice were crossed with RosaCRE-ERT2;Mcl1fl/+ mice and cohorts aged until mammary tumours reached 5 mm diameter at which time ubiquitous deletion of one allele of Mcl1 was achieved by tamoxifen administration and tumour growth monitored until clinical endpoint." (PMID 33785871, 2021). "Moreover, MCL-1 protein expression levels are linked to poor outcome, are required for breast cancer development, and targeting of MCL-1 hampers triple-negative breast cancer development in vivo." (PMID 33308268, 2020). "This hypothesis would require further investigation, but is supported by observations that the MCL1 gene is more frequently amplified and overexpressed in ER+ breast cancers as compared to genes encoding all other Bcl-2 family members combined." (PMID 31595181, 2019). "Overexpression of MCL1 is implicated as a resistance factor for chemotherapeutics, such as paclitaxel and vincristine, by potentially restoring anti-apoptotic signaling and decreasing the sensitivity to chemotherapy in breast cancers." (PMID 31370269, 2019). "In support of this hypothesis, we found that MCL-1 expression was necessary for tumour development in the MMTV-PyMT mouse model of breast cancer, with outgrowth of tumours in the context of Mcl1 deficiency only occurring when cells escaped deletion of Mcl1." (PMID 29339815, 2018). "The expression of Mcl-1 was associated with poor prognosis of breast cancer patients." (PMID 28301598, 2017). "In addition, increased expression of Mcl-1 has been associated with poor prognosis in breast cancer." (PMID 23284704, 2012). "However, in all the breast cancer cell lines examined, we were unable to detect any prolonged association of Mcl-1 and Mule between 0 and 36 h of CHX treatment." (PMID 21730980, 2011). "Our results indicate that unstable association between Mule and Mcl-1 may contribute to decreased ubiquitination and degradation of Mcl-1 in breast cancer cells." (PMID 21730980, 2011). "This suggests that mechanisms other than Mcl-1 associating proteins could be operating in breast cancer cells leading to increased stability of Mcl-1." (PMID 21730980, 2011). "Furthermore, the MCL1 inhibitor, S63845, could potentiate apoptosis when combined with a low dose of RMC-6272, suggesting that MCL1 loss is rate limiting at triggering apoptosis in ER+ breast cancer cells." (PMID 37264081, 2023). "To determine whether the conventional anti-apoptotic role of MCL-1 was responsible for mammary tumour sensitivity to MCL-1 loss/inhibition we deleted Bax and Bak to bypass the canonical anti-apoptotic function of MCL-1 (regulation of mitochondrial outer membrane permeabilization)." (PMID 33785871, 2021). "In order to determine whether low expression level of miR-26a is associated with high expression level of MCL-1 in breast cancer cells, we further performed Western blot analyses in the 2 immortalized normal mammary epithelium cell lines and 4 breast cancer cell lines." (PMID 23750239, 2013).
breast carcinoma (continued). "Currently, both CDK8 and Mcl-1 are being actively pursued as therapeutic targets in breast cancer in general and triple-negative breast cancer specifically." (PMID 41596544, 2026). "A study demonstrated that the overexpression of splicing factors SRSF1, hnRNP K, and hnRNP F/H1 induced splice-switching in Mcl-1, increasing the levels of Mcl-1L in human breast cancer cells." (PMID 40282556, 2025). "MDA-MB-231 breast cancer cells were transduced with individual MCL1-degrader fusions, and endogenous MCL1 protein levels were assessed by Western blot 72 hrs post-transduction." (PMID 41279570, 2025). "Immunohistochemical staining of MCL-1 protein was performed using tissue microarrays derived from formalin-fixed, paraffin-embedded breast cancer tissues." (PMID 40612845, 2025). "ELK1, but not SRF or STAT3, was reported to regulate both the basal and epidermal growth factor induced MCL1 transcription in breast cancer cells." (PMID 40075071, 2025). "In a chicken chorioallantoic membrane (CAM) model in ovo, co-engraftment of breast cancer cells and bCAFs with reduced MCL-1 expression leads to heightened peritumoral vascular density, driven by VEGF." (PMID 40783386, 2025). "The results of our current study demonstrate for the first time that inhibition of Mcl-1 protein by MIM1 in breast cancer cells induces cell cycle arrest at the G2/M or S phase." (PMID 40892149, 2025). "We also showed successful HSMCB PRIMAB tracking with CDK-9 inhibitor and with MCL-1 mimetic in breast cancer xenograft." (PMID 40507334, 2025). "The treated breast cancer cell line had markedly reduced Mcl-1 levels and increased cleaved caspase 3, signaling the induction of apoptosis." (PMID 41149606, 2025). "A previous study reported that combined treatment with dasatinib and the Myeloid cell leukemia-1 (MCL1) inhibitor (BIMs2A) can suppress breast cancer metastasis." (PMID 41462902, 2025). "Curcumin mediates NOX4-induced mitochondrial ROS and then it also induces caspase-dependent apoptotic cell death through the reduction in c-FLIP and Mcl-1 expression in head and neck squamous cell carcinoma, human breast cancer, and human glioma cells." (PMID 41465451, 2025). "By doing so, we hope to enhance our understanding of TNBC's complex response to MCL1-targeted therapy and ultimately improve treatment outcomes for patients with this aggressive subtype of breast cancer." (PMID 38762181, 2024). "MCL-1 protein was upregulated among many tumors (e.g. breast cancer, colon cancer, multiple myeloma)." (PMID 38706892, 2024). "To validate this phenomenon, we assessed the ability of TMCO1 silencing to promote apoptosis to MCL-1 inhibition in another invasive basal breast cancer cell line, HCC1806." (PMID 39353922, 2024). "A switch in the alternative splicing of MCL-1 was shown in breast cancer, which was characterized by upregulation of MCL-1L compared to the increased level of MCL-1S in normal tissue." (PMID 39695189, 2024). "Specifically, in human breast cancer, a study using MMTV-PyMT mice revealed high MCL-1 expression in both primary mammary tumors and metastatic lesions." (PMID 39012900, 2024). "Together, our data suggested RMC-6272 triggers apoptosis in breast cancers through regulating 4EBP1/eIF4E and downstream protein levels of the key anti-apoptotic protein MCL1." (PMID 37264081, 2023). "For example, breast cancer, especially ER-positive breast cancer, is characterized by amplification of Mcl-1 expression, which was correlated with a high tumor grade and poor prognoses in patients." (PMID 37537243, 2023). "The myeloid cell leukemia-1 (Mcl-1) siRNA nioplex treatment significantly decreased mRNA expression and breast cancer cell growth." (PMID 37896184, 2023).